NEURL3 (neuralized E3 ubiquitin protein ligase 3)
Description:
E3 ubiquitin-protein ligase that plays a role in various biological processes such as lung development or innate immunity. Seems to utilize UBE2E1. Promotes innate antiviral response by catalyzing 'Lys-63'-linked ubiquitination of IRF7. Also inhibits hepatitis C virus assembly by directly binding to viral E1 envelope glycoprotein to disrupt its interaction with E2. Plays an essential role in TLR4-mediated activation of MAPK pathways by promoting 'Lys-48'-linked polyubiquitination of the phosphatase DUSP1/MKP1.
Synonyms: LINCR; LOC93082; RNF132
Tractability: No criterion of Open Targets' tractability assessment is met for any kind of drug.
Gene: Protein-coding gene on chromosome 2 (96,497,644 to 96,508,153, reverse strand). Ensembl gene ENSG00000163121.
Subcellular location: Cytoplasm
Gene Ontology:
Molecular function: ubiquitin protein ligase activity
Biological process: positive regulation of proteasomal protein catabolic process; ubiquitin-dependent endocytosis; protein ubiquitination
Cellular component: cytoplasm; early endosome
Genetic constraint (gnomAD): Loss-of-function variants: 18 observed, 12.18 expected, observed/expected ratio (o/e) 1.48, 90% interval 1 to 1.91. The synonymous counts are far from expectation, so gnomAD's model fits this gene poorly and the ratio says little. Missense variants: 331 observed, 316.1 expected, observed/expected ratio (o/e) 1.05, 90% interval 0.96 to 1.15. Synonymous variants: 174 observed, 130.75 expected, observed/expected ratio (o/e) 1.33, 90% interval 1.17 to 1.51.
Homologues: Orthologues: chimpanzee NEURL3 (98% identical), macaque NEURL3 (90% identical), dog NEURL3 (76% identical), pig NEURL3 (73% identical), rabbit NEURL3 (71% identical), mouse Neurl3 (67% identical), rat Neurl3 (66% identical), guinea pig NEURL3 (64% identical). Paralogues in human: NEURL1B (39% identical), NEURL1 (37% identical), NEURL4 (30% identical).
Diseases named in the same sentence as NEURL3 in open-access papers:
NEURL3 is named in the same sentence as 11 diseases in open-access papers, as found by Europe PMC text mining. Sharing a sentence is not in itself a finding about the gene and the disease. The quoted sentences say what the papers report.
nasopharyngeal carcinoma (2 papers, 2024). A carcinoma arising from the nasopharyngeal epithelium. "Another downregulated tumor suppressor is the E3 ligase NEURL3, which suppresses the epithelial–mesenchymal transition and metastasis in nasopharyngeal carcinoma." (PMID 39796711, 2024).
lung carcinoma (1 paper, 2022). "In addition to mRNA level, the increased protein level of NEURL3 was detected in the A549 lung cancer cell line upon VSV infection." (PMID 35792897, 2022).
viral infection (1 paper, 2022). "More importantly, the Neurl3−/− mice exhibited increased susceptibility to viral infection, which was assessed by survival curve, histological analysis, and proteomic study." (PMID 35792897, 2022). "We next used VSV to infect WT and Neurl3−/− mice to evaluate the function of NEURL3 on the susceptibility of mice to viral infection." (PMID 35792897, 2022). "Accordingly, Neurl3−/− mice produced less type I IFNs and exhibited increased susceptibility to viral infection." (PMID 35792897, 2022). "Accordingly, Neurl3−/− mice produce less type I IFNs and exhibit increased susceptibility to viral infection." (PMID 35792897, 2022). "In accordance with the stimulatory effects of NEURL3 on host antiviral response, increased lethality was detected in Neurl3−/− mice as relative to their littermate controls post‐viral infection." (PMID 35792897, 2022). "In concomitant with IRF7 induction, NEURL3 is upregulated by NF‐κB signaling in the late phase of viral infection." (PMID 35792897, 2022). "The E3 ubiquitin ligase NEURL3 was identified as a strong IRF7 binding partner during viral infection." (PMID 35792897, 2022). "The level of IRF7 ubiquitination was reduced in Neurl3−/− livers than that in wild type controls following viral infection, further confirming NEURL3 as the E3 ubiquitin ligase of IRF7." (PMID 35792897, 2022). "Using GO analysis, pathways including defense responses to virus and type I interferon signaling were enriched in livers of WT mice as compared with Neurl3−/− mice following viral infection." (PMID 35792897, 2022). "Our data thus demonstrate that p65 plays an important role in NEURL3 upregulation during viral infection." (PMID 35792897, 2022). "Our data thus indicate that NEURL3 can facilitate host immune response against viral infection." (PMID 35792897, 2022). "Our results thus demonstrate that IRF7 selectively interacts with NEURL3 during viral infection." (PMID 35792897, 2022). "In addition to viral infection, NEURL3 can be induced in the alveolar epithelial cells upon exposure to LPS." (PMID 35792897, 2022). "In addition to the liver, similar results were also detected in lungs from WT or Neurl3−/− mice post‐viral infection." (PMID 35792897, 2022). "Moreover, we also employed the anti‐IRF7 antibody to pulldown the endogenous IRF7 and assessed the ubiquitin modification of IRF7 from livers in wild type or Neurl3−/− mice following viral infection." (PMID 35792897, 2022). "Inducible NEURL3 was detected in the liver, lung, brain, and kidney during viral infection." (PMID 35792897, 2022). "Consistent with the quantitative proteomic results, qRT‐PCR results showed that along with a lower level of viral titration, higher levels of ISGs such as Isg15, Oasl2, and Stat1 were detected in livers of WT mice than those from Neurl3−/− mice post‐viral infection." (PMID 35792897, 2022). "Notably, the remarkable induction of NEURL3 mainly occurred at 12, 24, and even 48 h post‐viral infection, which was considered the late phase of viral infection." (PMID 35792897, 2022). "Given that IRF7 plays a predominant role in the late phase of viral infection, it is conceivable that NEURL3 preferentially regulates the activity of IRF7 rather than IRF3." (PMID 35792897, 2022). "However, during viral infection, the expression of ISGs including DHX58, IFITM3, ISG15, and OASL was upregulated in the livers of WT mice, while Neurl3−/− livers expressed a higher level of proteins related to inflammatory response such as S100A9 and CD47." (PMID 35792897, 2022). "In addition to viral infection, we found that activation of RIG‐I‐like (RLR) signaling (RIG‐I and MAVS) rather than IFN signaling contributed to the transactivation of NEURL3." (PMID 35792897, 2022). "Moreover, we performed qRT‐PCR experiments to assess the expression of Neurl3 in the tissues of C57BL/6 mice with or without viral infection." (PMID 35792897, 2022).
cancer (4 papers, 2022 to 2025). A tumor composed of atypical neoplastic, often pleomorphic cells that invade other tissues. "In light of the essential role of C217 in NEURL3‐mediated innate immune response, it is conceivable that the C217Y mutation can impair host antitumor immune response and facilitate cancer development." (PMID 35792897, 2022). "In contrast, the function of NEURL3 is not well understood and its association with cancer has not been reported." (PMID 38069335, 2023). "New attempts should focus on the role of NEURL3 in the modulation of cancer immune escape." (PMID 35792897, 2022). "However, the role of NEURL3 in human cancer has not yet been explored." (PMID 35954204, 2022).
infection (3 papers, 2020 to 2024). The state of being infected such as from the introduction of a foreign agent such as serum, vaccine, antigenic substance or organism. "The upregulated expression of the C3 and ZC3H12A genes and upregulated expression of antiviral genes, such as CXCL8 and NEURL3, occurred at 9 h post-infection." (PMID 39872814, 2024). "Among the infection-specific ISGs upregulated during ΔHA-Cre infection are genes associated with apoptosis (Ripk2, Casp1, Ifi27, Pmaip1) and E3 ubiquitin ligases and proteasome genes, some of which are known to be involved in MHC-I antigen processing (Neurl3, Rnf19b, Psmb9)." (PMID 32790753, 2020).
tumor (3 papers, 2024 to 2025). "Low expression of NEURL3 was associated with poor prognosis and indicated tumor metastasis in NPC patients." (PMID 38191501, 2024). "Our findings underscore the wide-ranging functional capabilities of NEURL3 as an E3 ubiquitin ligase in governing the degradation of target proteins, and offer a partial explanation for the anti-tumor biological role of NEURL3 in NPC." (PMID 38191501, 2024). "Specifically, the restoration of Vimentin expression could fully reverse the tumor suppressive effect of NEURL3 overexpression in NPC cells." (PMID 38191501, 2024). "Furthermore, we unequivocally revealed an inhibitory impact of NEURL3 on NPC metastasis, broadening our understanding of the role of NEURL3 in tumor biology." (PMID 38191501, 2024).
bacterial infection (1 paper, 2022). "In light of the interaction between NEURL3 and IRF3 or IRF7, we thus hypothesize that NEURL3 can also affect inflammation through the regulation of interferon signaling during bacterial infection." (PMID 35792897, 2022).
NEURL3 also shares sentences with these, for which no sentence is quoted: endotoxemia (1 paper); esophageal squamous cell carcinoma (1); Hepatitis (1); pancreatitis (1).